MTOR (mechanistic target of rapamycin kinase)
Diseases named in the same sentence as MTOR in open-access papers (continued):
Sharing a sentence is not in itself a finding about the gene and the disease.
diabetic nephropathy (continued). "In conclusion, our study demonstrated that upregulation of TXNIP mediates dysfunction of tubular autophagy and mitophagy through the mTOR signaling pathway and contributes to the development of diabetic nephropathy." (PMID 27381856, 2016). "Activation of the PI3K/AKT/mTOR pathway is a crucial molecular event in human clear cell renal cell carcinoma (ccRCC), and is also upregulated in diabetic nephropathy." (PMID 25948777, 2015). "The anti-fibrotic effects of mTOR inhibition have been reported in various rat models of diabetic nephropathy, glomerulosclerosis, tubulointerstitial fibrosis, and liver cirrhosis." (PMID 25358403, 2014). "Over the past few years, the role of mTOR in the pathogenesis of diabetic nephropathy has received increased attention." (PMID 25126552, 2014). "The activation of mTOR plays a pivotal role in the renal pathologic characteristic of diabetic nephropathy (DN)." (PMID 25530759, 2014). "Sustained activation of mTOR is seen in fibrotic renal diseases such as diabetic nephropathy in which TGFβ plays an important role in developing fibrosis." (PMID 25333702, 2014). "Of the three nutrient-sensing pathways, the pathological roles of mTOR and the therapeutic potential of rapamycin, an inhibitor of mTOR, in diabetic nephropathy are increasingly being examined in experimental animal models." (PMID 25126552, 2014). "The mammalian target of rapamycin (mTOR) pathway plays an important role in the development of diabetic nephropathy and other age-related diseases." (PMID 26464852, 2014). "Caution is necessary when interpreting the role of mTOR in diabetic nephropathy because many of the current insights regarding mTOR are derived from pharmacological inhibition of mTOR by rapamycin." (PMID 25126552, 2014). "Among them, the activation of mammalian target of rapamycin (mTOR) signaling pathway is involved in the pathogenesis for several kidney diseases, such as diabetic nephropathy and the autosomal dominant polycystic kidney disease." (PMID 24379901, 2013). "Previous experimental studies in diabetic nephropathy and crescentic nephropathy animal models have found that mTOR is upregulated in podocytes and damaged podocytes." (PMID 23667674, 2013). "Their study found that the abnormal activation of mTOR played a key role in podocyte injury and proteinuria found in human and rat diabetic nephropathy." (PMID 23667674, 2013). "Although mTOR activity was increased in both human and animal kidneys with diabetic nephropathy, genetic deletion of mTORC1 in mouse podocytes induced proteinuria and progressive glomerulosclerosis." (PMID 22693670, 2012). "Increased mTOR activity has been implicated in several glomerular diseases, such as membranous nephropathy, focal segmental glomerulosclerosis (FSGS), minimal change disease, and diabetic nephropathy." (PMID 41509918, 2026). "Additionally, exosomes containing miR-486 secreted by adipose-derived stem cells (ADSCs) have been shown to enhance autophagic flux in podocytes by inhibiting Smad1/mTOR signaling, thereby ameliorating diabetic nephropathy." (PMID 41390431, 2025). "Recent independent studies have revealed a role for mTOR signaling in podocyte function and diabetic nephropathy, suggesting that inhibiting mTOR could offer therapeutic benefits." (PMID 41356921, 2025). "In this study, we explored the mechanism by which DDIT4 influences the polarization phenotypic transformation of macrophages and inflammation through the regulation of mTOR signaling pathway, providing a new mechanism and target for the treatment of diabetic nephropathy." (PMID 40916492, 2025). "Additionally, we highlight the research progress in the treatment of diabetic nephropathy with drugs and various molecules interfering with the mTOR signaling pathway, providing a theoretical reference for the treatment and prevention of diabetic nephropathy." (PMID 39717716, 2025).
diabetic nephropathy (continued). "For example, DHM was reported to mediate the AMPK-PGC-1a-SIRT3 signaling pathway to improve skeletal muscle insulin sensitivity and promote autophagy by activating AMPK/mTOR signaling pathway, thereby reducing diabetic kidney injury and even delaying the progression of diabetic nephropathy." (PMID 38275711, 2024). "Therefore, a selective inhibitor of mTOR sirolimus attenuates the development of diabetic nephropathy." (PMID 39656379, 2024). "In 2019, his group reported that ADSC-exosomes improved diabetic nephropathy symptoms by increasing the expression of miR-486, which led to the inhibition of the Smad1/mTOR (Mothers Against Decapentaplegic family 1/Mammalian target of rapamycin) signaling pathway in podocytes." (PMID 38988671, 2024). "TPL can protect the kidney by mitigating epithelial mesenchymal transition (EMT) of hexokinase (HK-2) cells through PI3K/Akt signaling pathway and inhibiting Akt/mTOR signaling pathway, thus inhibiting the proliferation of glomerular tethered cells in diabetic nephropathy." (PMID 37608889, 2023). "Furthermore, emodin has been found to suppress cell apoptosis and improve podocyte autophagy through the AMPK/mTOR signaling pathway in the renal organs of rats with diabetic nephropathy." (PMID 37702819, 2023). "Resveratrol, triptolide, astragaloside IV, ginsenoside Rg1, and ferulic acid can exert their effects in the treatment of diabetic nephropathy through activation of miR-383-5p, ERK signaling, miR-141-3p/PTEN/Akt/mTOR pathway, and AKT/GSK3β/β-linked protein pathway-mediated autophagy, respectively." (PMID 37810881, 2023). "The AMPK/mTOR signaling pathway is also closely involved in diabetic nephropathy." (PMID 36832842, 2023). "Additionally, GLP-1, a crucial pro-intestinal hormone, has been found to stimulate autophagy through the AMPK/mTOR signaling pathway and related proteins, ultimately alleviating diabetic nephropathy." (PMID 37810881, 2023). "Interestingly, a recent study conducted in mice with diabetic nephropathy showed that butyrate can reduce skeletal muscle atrophy in diabetic nephropathy by stimulating the FFA2-mediated PI3K/AKT/mTOR signaling pathway." (PMID 36166104, 2023). "Tripterygium wilfordii and its active components upregulate autophagy in diabetic kidney disease (DKD) mice through the mTOR/Twist1 signaling pathway, reduce podocyte transdifferentiation and apoptosis, reduce interleukin-4 overexpression, enhance cell viability, and inhibit podocyte apoptosis." (PMID 36003509, 2022). "Accumulated evidence has confirmed the crucial role of the mTOR pathway in diabetic nephropathy." (PMID 35620059, 2022). "ROS activate the AKT/mTOR signalling pathway in diabetic nephropathy." (PMID 36550401, 2022). "This confirmed the activation of the mTOR pathway in diabetic nephropathy." (PMID 35620059, 2022). "Besides, the formula comprising Astragalus mongholicus Bunge and Panax notoginseng (Burkill) F.H. Chen protects the kidney from inflammatory damage in diabetic nephropathy, possibly by inhibiting mTOR and activating PINK1/Parkin signaling to promote autophagy." (PMID 35903668, 2022). "The results of this experiment indicate that the PI3k/Akt/mTOR signaling pathway is activated, and autophagy is inhibited in diabetic nephropathy; however, the signaling pathway is inhibited, and autophagy is reactivated after GLP treatment, indicating that GLP plays a renal protective role." (PMID 35299891, 2022). "Collectively, marker genes of immune cells EIF4B, RICTOR, and PRKCB in the mTOR pathway might participate in diabetic nephropathy progression." (PMID 35620059, 2022). "Therefore, blocking the mTOR pathway can significantly increase the number of Treg cells, which promotes the improvement of diabetic nephropathy." (PMID 35251009, 2022).
diabetic nephropathy (continued). "In conclusion, the effect of GLP amelioration diabetic nephropathy may be via the PI3k/Akt/mTOR signaling pathway by inhibition of the apoptosis and inflammation and activation of the autophagy process." (PMID 35299891, 2022). "Previous studies have reported that G. biloba extract can prevent renal fibrosis by modulating Akt/mTOR signaling in diabetic nephropathy; it can also reduce the occurrence of liver fibrosis through NF-κB and TGF-β1 or by regulating p38 MAPK, NF-κB, and Bcl-2/Bax signaling to relieve liver fibrosis." (PMID 35707278, 2022). "The mTOR pathway participates in the pathogenesis of diabetic nephropathy." (PMID 35620059, 2022). "Additionally, blockade of mTOR activation can suppress the progression of diabetic kidney disease, primarily by reducing glomerular hyperpermeability and mitigating proteinuria." (PMID 34627341, 2021). "Also, in diabetic nephropathy, quercetin improves the renal function by suppression of progression of renal fibrosis and mammalian target of rapamycin (mTOR/p70S6) kinase (p70S6K) signaling which mediates renal tubular epithelial-mesenchymal transition." (PMID 33593237, 2021). "Overactivation of PI3K/Akt/mTOR is involved in diabetic retinopathy, diabetic nephropathy, and IR." (PMID 33880375, 2021). "The aetiology of proteinuria may be related to mTOR inhibitors, chronic graft dysfunction, calcineurin inhibitor nephrotoxicity, and diabetic nephropathy." (PMID 32922997, 2020). "Moreover, cinacalcet, a type II agonist of calcium-sensing receptor (CaSR), ameliorated diabetic nephropathy in db/db mice via regulating AMPK/mTOR-mediated autophagy." (PMID 31936109, 2020). "Also, triptolide (TP), a traditional Chinese medicine, reduced fibrosis by increasing autophagy via the miR-141-3p/PTEN/protein kinase B (Akt)/mTOR pathway in STZ-induced diabetic nephropathy in high fat diet (HFD)-fed rats." (PMID 31936109, 2020). "Indeed, mTORC1 target genes and mTOR mRNA itself were reported to be induced in glomeruli from patients with diabetic nephropathy." (PMID 32191726, 2020). "In agreement with this hypothesis, a recent work demonstrated that Neat1 repression led to decreased proliferation and fibrosis in diabetic nephropathy via activation of the Akt/mTOR signaling pathway." (PMID 31634682, 2019). "However, increased mTOR activity accompanied human diabetic nephropathy, characterized by early glomerular hypertrophy and hyperfiltration." (PMID 25755650, 2015). "Moreover, in diabetic nephropathy, there is an early activation of mTOR signaling leading to hypertrophy, proliferation and apoptosis in cells of the mesangium and proximal tubular cells." (PMID 25948777, 2015). "The PI3K/AKT/mTOR pathway is also upregulated in human diabetic nephropathy." (PMID 25948777, 2015). "However, using rapamycin we and others have recently shown involvement of mTOR to contribute to renal cell pathology found in diabetic kidney disease including kidney hypertrophy and matrix protein expression." (PMID 25333702, 2014). "Thus, knowledge of the role of mTOR in diabetic nephropathy is largely limited to the role of mTORC1." (PMID 25126552, 2014). "Thus, it is evident that mTOR plays a central role in the development of the major features of diabetic nephropathy, although additional mechanisms are likely to be involved." (PMID 25126552, 2014). "Thus, kidney tissue-specific analysis of mTORC1- and mTORC2-dependent signaling in mice is required to further understand the functional role of mTOR in diabetic nephropathy." (PMID 25126552, 2014). "Several studies have shown that hyperactivation of the mTOR pathway in diabetic nephropathy plays a pivotal role in the hypertrophy of existing glomerular and tubular cells and is associated with podocyte injury and the progressive decline of glomerular filtration rates." (PMID 22028701, 2012).
diabetic nephropathy (continued). "Therefore, it is important to test if reduction of podocyte mTOR activity can be harnessed as a potential therapeutic strategy to treat diabetic nephropathy." (PMID 22693670, 2012). "Recent studies also indicate the importance of the mTOR signaling pathway in podocytes in the progression of glomerular disease, so the use of mTOR inhibitors in immunosuppressive therapy may have a potential role in the prevention of diabetic nephropathy." (PMID 39941214, 2025). "The findings are consistent with the results of gene set enrichment analysis (GSEA), indicating that DDIT4 may modulate cellular oxidative stress levels through involvement in the VDR/mTOR/p70s6k/4E-BP1 signaling pathway, thereby ameliorating pathological damage associated with diabetic nephropathy." (PMID 38567351, 2024). "The activation of mTOR was crucial to the preservation of glomerular podocyte function, as well as the occurrence of glomerular and tubular cell hypertrophy and podocytes damage, on the contrary, mTOR inhibition might preserve podocytes and prevent the progression of diabetic nephropathy." (PMID 38632264, 2024). "This study found that compared with the control group, the expression of p-PI3K, p-Akt, and p-mTOR increased in the diabetic group had significantly decreased after GLP treatment, indicating that GLP may improve diabetic nephropathy by inhibiting the PI3k/Akt/mTOR signaling pathway." (PMID 35299891, 2022). "Qiao and colleagues have shown that mTOR and Nrf2 also interact via the β-TrCP/Nrf2 pathway, wherein mTOR promotes Nrf2 nuclear translocation through inhibiting β-TrCP expression; this process is critical to the initiation and progression of diabetic nephropathy." (PMID 34012501, 2021). "Further investigation into the role of the important member of mTOR, the protein kinase PKC, was centered upon early diabetic nephropathy (albuminuria) in the STZ diabetic rat." (PMID 37759585, 2023). "Similarly, DMY could also mediate the AMPK-PGC-1α-SIRT3 signaling pathway to improve skeletal muscle insulin sensitivity and promote autophagy by activating the AMPK/mTOR signaling pathway, which can alleviate diabetic kidney injury and even retard the progression of diabetic nephropathy." (PMID 37732125, 2023). "The expression of mTOR pathway markers EIF4B, RICTOR, and PRKCB was verified in kidney tissues from the control group and the diabetic nephropathy rat model group." (PMID 35620059, 2022). "The GSE111154 and GSE142025 datasets were utilized for validating the expression of mTOR pathway markers EIF4B, RICTOR, and PRKCB in the kidneys from controls and diabetic nephropathy patients." (PMID 35620059, 2022). "In diabetic nephropathy, lncRNA SPAG5-AS1 activates the AKT/mTOR pathway through upregulation of SPAG5 to foster apoptosis and abate autophagy in high glucose- (HG-) treated human podocytes (HPCs)." (PMID 36118675, 2022). "Several signaling pathways seem entangled in the genesis of damage to podocytes’ mitochondria and consequent proteinuria in Diabetic Kidney Disease (DKD), particularly the mammalian target of rapamycin (mTOR), Wnt/β-catenin and AMPK signaling pathways." (PMID 33673215, 2021). "In the conditions of diabetic nephropathy and lipopolysaccharide-induced acute kidney injury, enhancing autophagy with some therapeutics through inhibition of the PI3K/AKT/mTOR pathway ameliorates kidney function." (PMID 33924028, 2021). "Therefore, the role of the mTOR signaling pathway in the formation of diabetic nephropathy may be cell specific, and mTOR in different cells may play different roles in the various stages of diabetic nephropathy." (PMID 34627341, 2021). "In diabetic nephropathy conditions, dihydromyricetin promoted autophagy through the regulation of miR-155-5p and its target gene PTEN and PI3K/AKT/mTOR pathway under both in vitro and in vivo conditions." (PMID 34681206, 2021).
diabetic nephropathy (continued). "Podocyte injury is a prediction marker of diabetic nephropathy (DN), and AKT/mTOR pathway–mediated inhibition of autophagy is widely reported to contribute to podocyte damage." (PMID 31957155, 2020). "In models of diabetic nephropathy, many pharmaceutical agents have been shown to prevent podocyte injury via regulating AMPK/mTOR-mediated autophagy." (PMID 31936109, 2020). "Dysregulation of the antagonistic interplay between the mechanistic target of rapamycin (mTOR) and AMP-activated protein kinase signaling pathways impairs mitochondrial quality control, contributing to the pathogenesis of AKI and diabetic nephropathy through disrupted cellular homeostasis." (PMID 40827445, 2025). "In the context of the pathological mechanism of diabetic nephropathy, it has been pointed out that high glucose levels affect AMPK phosphorylation by inducing phosphorylation on Ser2448 and this activates mTOR, resulting in induced extracellular matrix accumulation in renal fibroblasts." (PMID 36832842, 2023). "Recent studies have shown that mesenchymal stem cell (MSC)-derived exosomes could reduce myocardial ischemia/reperfusion injury and diabetic nephropathy by inducing autophagy via AMPK/mTOR and Akt/mTOR pathways." (PMID 36805797, 2023). "Additionally, ROS induces EMT via the TGF-β1/PI3K/AKT/mTOR pathway in diabetic nephropathy, and tamoxifen ameliorates obstructive nephropathy through Src and the PI3K/AKT/mTOR pathway." (PMID 35015734, 2022). "The aim of this work was to evaluate three autophagy regulators; Rubicon (RUBCN), mTOR and Sestrin-2 (SESN2) as clinically applicable biomarkers of diabetic nephropathy; and to assess if they can be used to predict the development of nephropathy in diabetic patients." (PMID 36476132, 2022). "In diabetic nephropathy, LINC00084 exhibited a fibrosis effect to increase the expression of TGF-β1, fibronectin, and collagen IV in the glucose-induced mouse mesangial cells via activating Akt/mTOR signaling." (PMID 34442351, 2021). "Several lines of evidence suggest that the mTOR pathway may directly regulate GFB function, which is a key player in diabetic kidney disease." (PMID 34627341, 2021). "Moreover, the upregulation of mTOR activity has been documented in the renal IR model of AKI, a rat model of subtotal nephrectomy, glomerular injury, including diabetic nephropathy, and polycystic kidney disease." (PMID 31936109, 2020). "mTOR-dependent infiltration of macrophages and production of proinflammatory cytokines, such as MCP-1, might support inflammation during diabetic nephropathy." (PMID 25126552, 2014). "It has been reported that activation of the mTOR pathway is involved in the increased expression of profibrotic cytokines, such as TGF-β1 and connective tissue growth factor, and subsequent interstitial fibrosis in diabetic nephropathy." (PMID 22028701, 2012). "Furthermore, blockade of mTOR signaling with rapamycin was also able to inhibit CRP and /or high glucose-induced upregulation of collagen I and CTGF expression, demonstrating mTOR signaling as a central mechanism by which CRP promotes diabetic kidney disease in T2DN." (PMID 27221338, 2016).